STAT6 (signal transducer and activator of transcription 6)
Diseases named in the same sentence as STAT6 in open-access papers (continued):
Sharing a sentence is not in itself a finding about the gene and the disease.
lymphoma (31 papers, 2013 to 2025). A malignant (clonal) proliferation of B- lymphocytes or T- lymphocytes which involves the lymph nodes, bone marrow and/or extranodal sites. "The IL4 and BCR-induced mTOR activation was reduced by CREBBP mutants and augmented by mutant STAT6, establishing a link between STAT6 mutations and mTOR regulated pro-growth pathways in lymphoma." (PMID 39910284, 2025). "Despite identification of STAT6 mutations in other lymphomas, little is known about how mutation changes its function." (PMID 38285120, 2024). "This is not entirely surprising given the well described association of somatic STAT6 GOF mutations with various lymphomas, including FL." (PMID 37316763, 2023). "Our observation of relapsed lymphoma in the mother is not shared amongst the 20 other cases reported to date but is significant given the association of somatic STAT6 mutations associated with lymphoma." (PMID 37316763, 2023). "To conclude, our deep sequencing data revealed recurrent mutations in PCFBCL, such as in TNFRSF14, CREBBP and STAT6, thus classifying this lymphoma subtype as a distinct lymphoma entity within the spectrum of cutaneous lymphomas based on molecular grounds." (PMID 36358692, 2022). "Some institutes have used this method to detect somatic mutations including KRAS, XPO1, STAT6 and so on in some solid tumors and lymphomas." (PMID 32284750, 2020). "STAT6 has been found to be constitutively active in some leukemia and lymphoma types, associated with cell proliferation and transformation." (PMID 25669976, 2015). "Another important question concerns the molecular mechanisms underlying the repressive effect of STAT6 in lymphoma cells." (PMID 23852366, 2013). "Aberrant activation of STAT6 may predispose individuals with severe AD to lymphoma by promoting a pro-oncogenic immune environment." (PMID 40297814, 2025). "The clinical association of lymphoma in our kindred, along with previous data linking somatic STAT6 D419H mutations to follicular lymphoma suggest that patients with STAT6 GOF disease may be at higher risk of lymphomagenesis." (PMID 37316763, 2023). "In NHL, STAT6 is essential for IL-4 and IL-13 signaling, which supports Th2-mediated immune responses and aids in the survival and growth of lymphoma cells." (PMID 40321894, 2025). "The results demonstrated that lymphoma cells can activate the Notch-1 downstream STAT3/STAT6 signaling pathway." (PMID 38261741, 2024). "So, the constitutive activation of STAT6-sent signals facilitates the GC response, preventing apoptosis and favoring lymphoma survival." (PMID 39518937, 2024). "The expression levels of p-STAT3 and p-STAT6 in KO + lymphoma cell group were significantly inhibited compared with WT + lymphoma cell group, and their levels only slightly increased compared with WT group and KO group." (PMID 38261741, 2024). "The combination of iHSP110-33 and selinexor induces a synergistic reduction of STAT6 phosphorylation and of lymphoma cell growth in vitro and in vivo." (PMID 38773631, 2024). "STAT3 and STAT6 have lymphoma-promoting properties due to their activation of genes encoding for proteins such as MYC, BCL-XL and CYCLIND1." (PMID 36671496, 2023). "Lymphoma cell lines bearing these DNA-binding domain mutations permitted constitutive expression of IL-4-related genes that did not depend on STAT6 tyrosine phosphorylation at the Y641 site, suggesting a mechanism by which STAT6 GOF may promote lymphomagenesis." (PMID 37316763, 2023). "Our data support a model in which increased PARP14 levels drive a self-reinforcing microcircuit that promotes the assembly of the STAT6 enhanceosome complex in IL-4 stimulated STAT6MUT lymphoma cells, thereby further amplifying STAT6-dependent gene activation." (PMID 35851155, 2022). "RNA sequencing identified PARP14 -a transcriptional switch and co-activator of STAT6- among the top differentially upregulated genes in IL-4 stimulated STAT6MUT lymphoma cells and in STAT6MUT primary FL cells." (PMID 35851155, 2022).
lymphoma (continued). "Here we describe a therapeutically targetable PARP14-mediated self-reinforcing regulatory circuit that amplifies IL-4 induced STAT6-dependent gene expression in STAT6MUT lymphoma cells." (PMID 35851155, 2022). "Both compounds inhibited the IL-4 pathway by acting on IL-4Rα, JAK3, and STAT6 activation in lymphoma cells (DND39) and fibroblasts (NIH3T3)." (PMID 36364420, 2022). "Constitutive STAT6 activation is identified as a key feature of PMBL from other lymphoma and the NF-κB signaling pathway and the PI3K/AKT pathway are also reported to be activated in PMBL." (PMID 32850008, 2020). "A similar phenomenon was described recently by Pangault and co-workers, who found phosphorylated STAT6 expression in lymphoma cells in close proximity to T cells expressing PD1." (PMID 30203411, 2018). "STAT6 mutations, frequently detected in follicular lymphoma and other BCLs, point to a potential overlap in the IL-4/JAK/STAT6 signaling pathway involved in both AD and lymphoma pathogenesis." (PMID 40297814, 2025). "Whether lymphoma cells activate the STAT3/STAT6 signaling pathway in bone marrow-derived macrophages was investigated." (PMID 38261741, 2024). "We anticipate that this discovery will facilitate the recognition and targeted treatment of more affected individuals and, with time, a full definition of the human genotype-phenotype relationship caused by germline human STAT6 GOF variants will emerge, including understanding the risk of lymphoma." (PMID 36884218, 2023). "We could indeed confirm direct interaction of PARP14 and STAT6 in IL-4 stimulated lymphoma cells by IP of 3xFlag-tagged STAT6 and immunoblotting for PARP14." (PMID 35851155, 2022). "STAT4 and STAT6 genes are inversely regulated in CTCL and the loss of expression of the former may play a role in switching to Th-2 answer in the advanced lymphoma stages." (PMID 34948183, 2021). "Future studies could evaluate the possibility that CREBBP loss and STAT6 gain, possibly through BCL-xL, are sufficient to induce dFL-like lymphomas." (PMID 32555149, 2020). "Moreover, the combination of iHSP110-33/Selinexor could induce a synergistic reduction in STAT6 phosphorylation and lymphoma cell growth in vitro and in vivo." (PMID 40806458, 2025). "Then, lymphoma cells that mediate the Notch1 signaling in bone marrow-derived macrophages facilitate the activation of STAT3 and STAT6 in the same macrophages." (PMID 39518937, 2024). "Compared with WT group and KO group, KO + lymphoma cell group and WT + lymphoma cell group had significantly increased expression levels of STAT3 and STAT6, indicating that lymphoma cells can activate STAT3 and STAT6." (PMID 38261741, 2024). "One such recurrent mutation was in signal transducer and activator of transcription 6 (STAT6) at residue D419, found in 36% of relapsed/refractory GCB-DLBCL (rrDLBCL) and transformed lymphoma (rrTLy) samples." (PMID 38285120, 2024). "In KO + lymphoma cell + IXA4 group, the expressions of activated STAT3 and STAT6 were similar to that in WT + lymphoma group, while the expressions of p-STAT3 and p-STAT6 were significantly higher than those in KO + lymphoma cell group." (PMID 38261741, 2024). "Binding of IL-4 to its receptor (IL-4R) on lymphoma cells recruits JAK1/3 and activates STAT6 by phosphorylation of Y641." (PMID 35851155, 2022). "This highlights the oncogenic importance of IL-4/STAT6 pathway dysregulation across multiple lymphoma subtypes, not only MF." (PMID 40864740, 2025). "Expression of phosphorylated STAT6 without IL4/IL13 transcription has been demonstrated in PMBL, suggesting that STAT6 activation in these lymphomas is not due to an autocrine IL4/IL13 secretion." (PMID 37835560, 2023). "In addition, other cytokines, such as IL-3/15, interferon-α, and platelet-derived growth factor (PDGF), activate STAT6 in diverse cell lines and function in nonimmune systems and the pathogenesis of several diseases, including allergic responses, lymphomas, and leukemias." (PMID 40897694, 2025).
hepatocellular carcinoma (29 papers, 2019 to 2026). A malignant tumor that arises from hepatocytes. "In parallel, exoASO-STAT6, another candidate from Codiak’s exoASOTM platform, targets STAT6 in tumor-associated macrophages (TAMs), particularly within hepatic tumors such as hepatocellular carcinoma (HCC)." (PMID 41155971, 2025). "Analogously, several works have delineated a role for STAT6 in the development and metastasis of hepatocellular carcinoma (HCC), the most common type of primary liver cancer." (PMID 41409600, 2025). "Exposure of HuH7 and Hep3B hepatoma cells to IFN-α or IFN-β led to the formation of STAT2/STAT6 complexes, triggering the secretion of the anti-inflammatory interleukin-1 receptor antagonist (IL-1Ra)." (PMID 41409600, 2025). "STAT6 is highly expressed in a variety of human cancers and has been suggested to induce apoptosis and growth inhibition of hepatocellular carcinoma-derived cells by lowering RANKL expression." (PMID 36936916, 2023). "Consistent evidence suggests that STAT6 predicts poor prognosis in patients with hepatocellular carcinoma (HCC)." (PMID 34651050, 2021). "It has also been observed that hepatoma cells are capable of forming STAT2/STAT6 heterodimers in response to IFN type I; moreover, B cells stimulated with IFNα induce the formation of a STAT2/STAT6/IRF9 complex." (PMID 33076315, 2020). "STAT6 silencing significantly inhibited HepG2 and Hep3B hepatoma cells survival and proliferation." (PMID 41409600, 2025). "Alternatively, interferon-β can activate STAT6 in hepatoma cells." (PMID 34051858, 2021). "In hepatocellular carcinoma (HCC), ERβ attenuates pro-tumor inflammatory signaling by inhibiting the JAK/STAT6 pathway and tumor-associated macrophages polarization." (PMID 40507964, 2025). "It was concluded that targeting STAT5-and STAT6-related signalling pathways can inhibit the proliferation of CRC cells and induce CRC cell apoptosis, and Dong suggested that STAT5A, STAT5B and STAT6 expression may be potential prognostic markers of hepatocellular carcinoma." (PMID 35592424, 2022). "The M2 macrophages are abundant in hepatocellular carcinoma tumors, and correlate with the activation of the JAK1/STAT6 signaling pathway." (PMID 35269804, 2022). "For example, miR-210 in hepatocellular carcinoma (HCC)-derived exosomes can directly inhibit the expression of SMAD4 and STAT6, promoting angiogenesis." (PMID 34257272, 2021). "We found that STAT6 mediates two modules, while TFs such as JUN, AES, and AR mediate a module that affects the development and progression of hepatocellular carcinoma." (PMID 34651050, 2021). "In the regulation of transcription factors, STAT6 essentially regulates two functional disorder modules, while TF such as AR and ATF2 has a driving effect on one module, which affects the occurrence and development of hepatocellular carcinoma." (PMID 34651050, 2021). "Current studies have shown that in hepatocellular carcinoma (HCC), exosomal miR-210 secreted by HCC cells can be transferred to endothelial cells, thus promoting tumor angiogenesis by targeting SMAD4 and STAT6." (PMID 37602326, 2023). "For example, miR-210 contained inside hepatocellular carcinoma (HCC)-derived exosomes can stimulate angiogenesis by direct inhibition of SMAD4 and STAT6." (PMID 36619866, 2022). "Furthermore, IL4R plays an essential role in regulating hepatocellular carcinoma (HCC) cell survival, proliferation, and metastasis and regulates the activation of JAK1/STAT6 and Jnk/Erk1/2 pathways." (PMID 31540495, 2019).
glioma (27 papers, 2011 to 2025). A benign or malignant brain and spinal cord tumor that arises from glial cells (astrocytes, oligodendrocytes, ependymal cells). "Another study found that Th2 bias in glioma is associated with increased expression of STAT6, a transcription factor that regulates Th2 differentiation." (PMID 37610668, 2023). "To establish the mechanisms underlying downregulation of STAT6 transcript levels in human glioma, we first investigated the possibility of epigenetic silencing via CpG island hypermethylation." (PMID 31530290, 2019). "HSP70 is identified as a potential endogenous ligand for activating the SR-A1-linked STAT3 and STAT6 signaling cascades in the glioma microenvironment." (PMID 27367025, 2016). "Furthermore, Stat6-controlled expression of several lysosomal and extracellular proteases has been implicated in tissue destruction during pulmonary emphysema and is thought to contribute to the invasiveness of glioma tumours." (PMID 24314139, 2013). "Different studies have reported on the importance of IL-4 and GMCSF in glioma development and/or progression, showing an enhanced risk and worse outcome of GBM for people that carry certain polymorphisms in IL-4R and STAT-6 gene loci." (PMID 34880868, 2021). "STAT1, STAT3, STAT5A, STAT5B, and STAT6 mRNA expression levels were significantly upregulated in glioma (including GBM, astrocytoma, oligodendroglioma, and anaplastic astrocytoma), compared with normal brain tissues or neural stem cells." (PMID 34276757, 2021). "Using DNA methyltransferase inhibitors, such as five-azacitidine and decitabine, to restore STAT6 expression in STAT6-silenced gliomas can increase tumor cell death, which would provide a new treatment." (PMID 33013320, 2020). "Taken together, these observations demonstrate that STAT6 transcripts are downregulated in glioma tissues, leading to reduced STAT6 protein expression." (PMID 31530290, 2019). "Although it is well known that STAT3 is upregulated in glioma and plays a role in tumor progression and survival, little is known about STAT6 in this context." (PMID 31530290, 2019). "To obtain further evidence of STAT6 downregulation in gliomas, we performed immunohistochemical analyses using a brain glioma tissue array." (PMID 31530290, 2019). "Our study supports the application of epigenetic restoration of STAT6 with the aid of DNA methyltransferase inhibitors, such as 5-aza-2-deoxycytidine, for treatment of STAT6-silenced gliomas." (PMID 31530290, 2019). "In line with the results of MSP analyses, samples from high-grade gliomas showed prominent methylation, demonstrating a strong correlation between STAT6 downregulation and methylation of the STAT6 promoter in glioma." (PMID 31530290, 2019). "In this study, we demonstrated that STAT6 is downregulated in human glioma specimens as a result of CpG methylation of the STAT6 promoter." (PMID 31530290, 2019). "Recent developments in application of precision medicine to cancer treatment support the application of epigenetic restoration of STAT6 via DNA methyltransferase inhibitors (DNMTi) as a therapeutic strategy for STAT6-silenced gliomas." (PMID 31530290, 2019). "STAT6 silencing and consequent tumor-promoting effects are additionally observed in glioma stem-like cells (GSC)." (PMID 31530290, 2019). "In this study, we demonstrated that STAT6, an important signaling molecule in adaptive immunity, is frequently silenced in gliomas where hypoxia is a prominent feature." (PMID 31530290, 2019). "SR-A1 deletion promoted M2-like tumor-associated macrophage (TAM) polarization in mice by activating STAT3 and STAT6, which resulted in robust orthotopic glioma proliferation and angiogenesis." (PMID 27367025, 2016). "SR-A1 deletion in BMDMs increased this effect, suggesting that STAT3 and STAT6 signaling contribute to SR-A1 mediated BMDM polarization in the glioma microenvironment." (PMID 27367025, 2016).
glioma (continued). "Kaplan-Meier survival curves generated with Rembrandt -derived patient data also showed a correlation between higher STAT6 expression and decreased survival of glioma patients." (PMID 21595984, 2011). "In a Kaplan-Meier survival curve based on Rembrandt gene expression microarray and clinical data, there was a significant difference in survival (P < 0.05) between glioma patients with up- and down-regulated STAT6." (PMID 21595984, 2011). "Using microarray-based gene expression data and associated clinical reports, we generated a Kaplan-Meier survival curve based on differential STAT6 expression among 343 glioma patients." (PMID 21595984, 2011). "In a Kaplan-Meier survival analysis of 343 glioma patient datasets obtained from Rembrandt, lower STAT6 expression levels were indicative of a more favorable prognosis compared to patients with intermediate or high STAT6 expression." (PMID 21595984, 2011). "Kaplan-Meyer survival curves were generated to show the correlation between STAT6 gene expression and patient survival in 343 glioma patients and in a subset of patients with only GBM." (PMID 21595984, 2011). "Lastly, we showed the clinical and potentially prognostic significance of STAT6 up- and down-regulation in glioma patients by demonstrating that STAT6 expression inversely correlates with overall survival." (PMID 21595984, 2011). "We detected genes upregulated in PBT030 cells, such as SOX2, MYCN, NOS2, RUNX2, and VEGFA, while PBT147 cells upregulated level of PTEN, STAT6, CA9 and TLR2, demonstrating differences among PBT cell lines, which can be explained by various driving mutations and heterogeneity in glioma lines." (PMID 38449858, 2024). "In glioma cells, STAT6 negatively regulated HIF-1α expression via mTOR/S6K/S6 axis." (PMID 35600336, 2022). "Higher STAT6 levels were found in glioma tissues than normal brain tissues." (PMID 34276757, 2021). "Taken together, these results suggest a role for DNMT1 in STAT6 silencing in glioma." (PMID 31530290, 2019). "Next, we explored whether promoter methylation directly mediates the silencing of STAT6 in glioma tissue." (PMID 31530290, 2019). "Interestingly, we also found that the invasive capacity of H4 and A172 glioma cells was decreased following inhibition of STAT6 phosphorylation in a dose-dependent manner." (PMID 31123330, 2019). "However, the histone deacetylase inhibitor trichostatin A (TSA), had little effect on STAT6 expression, suggesting that methylation and not acetylation of DNA plays a dominant role in STAT6 silencing in glioma." (PMID 31530290, 2019). "Given the characteristic hypoxic microenvironment of glioma, we initially assessed whether STAT6 is related to HIF-1α expression, since HIF-1α is the critical mediator to hypoxic adaptation and survival." (PMID 31530290, 2019). "Moreover, STAT6 silencing and resulting tumor-promoting effects were consistently observed in glioma stem-like cells." (PMID 31530290, 2019). "Analysis of the Multiplex assay showed that only Signal Transducer and Activator of Transcription6 (STAT6) exhibited changes in phosphorylation that were consistent with the observed invasion pattern as well as with recently published data showing STAT6 to promote invasion in glioma cells." (PMID 31123330, 2019). "Our study demonstrates for the first time that SR-A1 could inhibit TAM differentiation toward an M2-like phenotype by suppressing STAT3 and STAT6 signaling in murine gliomas." (PMID 27367025, 2016). "Although the frequency of this event has not been fully explored, our results from querying TCGA ALGG and GBM datasets demonstrates that specific NAB2-STAT6 fusion events are rare in gliomas but that STAT6 fusions are recurrent events with several partners in adult GBM." (PMID 26817999, 2016). "It is also conceivable that STAT6 induces expression of a different subset of transcriptional targets based on the availability of transcriptional co-factors, which likely varies between low- and high-grade gliomas." (PMID 21595984, 2011).